LINC00525 (long independently transcribed non-coding RNA 525)
Gene: Long non-coding RNA gene on chromosome 7 (47,761,476 to 47,766,772, forward strand). Ensembl gene ENSG00000146666.
Diseases named in the same sentence as LINC00525 in open-access papers:
LINC00525 is named in the same sentence as 14 diseases in open-access papers, as found by Europe PMC text mining. Sharing a sentence is not in itself a finding about the gene and the disease. The quoted sentences say what the papers report.
chordoma (2 papers, 2020 to 2024). Chordomas are rare malignant tumors arising from embryonic remnants of the notochord in axial skeleton. "In addition, LINC00525 interacts with miR-31-5p and miR-125a-5p, acting as a carcinogenic molecule in chordoma." (PMID 38914670, 2024). "Similarly, LINC00525 acted as a sponge for miR-505 in chordoma cells." (PMID 33520999, 2020).
colorectal cancer (2 papers, 2020 to 2022). A primary or metastatic malignant neoplasm that affects the colon or rectum. "As a result of analysis in GSE110715, GSE32323, and GSE21510 datasets, LINC00525 was highly expressed in colorectal cancer tissues." (PMID 35156520, 2022). "Herein, it was found that LINC00525 and miR-338-3p reduced the expression of each other by binding, and miR-338-3p overexpression and LINC00525 knockdown inhibited UBE2Q1 protein expression in colorectal cancer cells." (PMID 35156520, 2022). "The aim of the present study was to discover a new mechanism for LINC00525 to regulate hypoxic glycolysis in colorectal cancer cells." (PMID 35156520, 2022). "Si-525-1, si-525-2, and si-525-3 all strongly reduced the expression of LINC00525 in colorectal cancer cells, with si-525-2 having the highest knockdown effect of the three siRNAs, decreasing LINC00525 expression to less than 25%." (PMID 35156520, 2022). "In this study, it was found that LINC00525 was highly expressed and promoted cell proliferation in colorectal cancer, which has been found in previous studies." (PMID 35156520, 2022). "miR-338-3p was identified as a downstream gene of LINC00525 through literature search and public databases to study the molecular mechanism of LINC00525 regulating hypoxic glycolysis in colorectal cancer cells." (PMID 35156520, 2022). "To investigate the functional role of hypoxia-induced LINC00525, we knocked down the expression of LINC00525 in colorectal cancer cells (SW620, SW1116, and LoVo) by transferring into si-525." (PMID 35156520, 2022). "Our goal is to discover a new mechanism for LINC00525 to regulate the Warburg effect of colorectal cancer cells under hypoxia." (PMID 35156520, 2022). "In this study, it was found that the expression of LINC00525 in human colorectal cancer cells (SW480, HCT116, HT29, SW620, SW1116, and LoVo) were all markedly higher than its expression in human normal colonic epithelial cells (NCM-460)." (PMID 35156520, 2022). "In colorectal cancer cells, hypoxia increasedLINC00525 expression, whereas knocking down LINC00525 reduced hypoxia-enhanced glycolysis." (PMID 35156520, 2022). "In conclusion, LINC00525 was highly expressed in colorectal cancer cells, and LINC00525 knockdown reduced the proliferation of colorectal cancer cells." (PMID 35156520, 2022). "Understanding how LINC00525 participates in the regulation of the Warburg effect in colorectal cancer provides novel insights on the issue." (PMID 35156520, 2022). "LINC00525 enhanced the stemness and chemoresistance of colorectal cancer through the miR-507/ELK3 axis." (PMID 32411181, 2020). "To study whether LINC00525 regulates the Warburg effect under hypoxic conditions, we first assessed the amount of LINC00525 in colorectal cancer cells (SW620, SW1116, and LoVo) using RT-qPCR analysis." (PMID 35156520, 2022). "miR-338-3p was identified as a downstream gene of LINC00525 to study hypoxic glycolysis because miR-338-3p was found to inhibit the proliferation and migration of colorectal cancer cells, as well as it was observed to be involved in the regulation of tumor cell glycolysis 1819." (PMID 35156520, 2022). "In addition, FISH staining analysis also showed that LINC00525 was mainly cytoplasmic localization in colorectal cancer cells." (PMID 35156520, 2022). "Similarly, the results of FISH staining also showed that si-525-1, si-525-2, and si-525-3 were all strongly knockdown the expression of LINC00525 in colorectal cancer cells, and si-525-2 has the best knockdown effect." (PMID 35156520, 2022). "Importantly, previous studies reported that LINC00525 is highly expressed in colorectal cancer tissues, and is related to the poor prognosis of colorectal cancer patients, and promotes the proliferation of colorectal cancer cells, and inhibits apoptosis." (PMID 35156520, 2022). "Furthermore, we found that LINC00525 is mostly present in the cytoplasm of colorectal cancer cells." (PMID 35156520, 2022).
colorectal cancer (continued). "Moreover, we also study the effect of different hypoxia conditions on the expression of LINC00525 in colorectal cancer cells (LoVo) and found that LINC00525 expression increased as the oxygen concentration decreased, and also increased as with the duration of hypoxia." (PMID 35156520, 2022). "It was also found that LINC00525 knockdown significantly decreased the relative enzymatic activity of LDHA and GLUT1 protein expression in colorectal cancer cells (SW620, SW1116, and LoVo) after being cultured under hypoxia." (PMID 35156520, 2022).
periodontitis (2 papers, 2020). An acute or chronic inflammatory process that affects the tissues that surround and support the teeth. "LINC00525 regulates immune response via plasma cells in periodontitis, while in non-small cell lung cancer, LINC00525 regulates cancer proliferation via the ceRNA network." (PMID 33664764, 2020). "The PCR results, consistent with the microarray chip data, demonstrated that all the differentially expressed lncRNAs (FAM30A, GUSBP11, and LINC00525) were upregulated in periodontitis compared with those in controls." (PMID 32411181, 2020).
colon carcinoma (1 paper, 2023). "LINC00525 expression is remarkably elevated in colon cancer cells and tissues, and LINC00525 overexpression has been linked to adverse prognosis in colon carcinoma." (PMID 37744265, 2023).
lung adenocarcinoma (1 paper, 2024). A carcinoma that arises from the lung and is characterized by the presence of malignant glandular epithelial cells. "The expression of LINC00525 is up-regulated in lung adenocarcinoma." (PMID 38914670, 2024).
cancer (4 papers, 2020 to 2024). A tumor composed of atypical neoplastic, often pleomorphic cells that invade other tissues. "Studies have shown that LINC00525 is highly expressed in a variety of cancers." (PMID 38914670, 2024). "GUSBP11 and LINC00525 were found to participate in the development of several cancers." (PMID 32411181, 2020). "LINC00460, LINC00525, FAM111B and ZWINT were upregulated and hsa-miR-338 was downregulated in most cancers." (PMID 35406786, 2022). "LINC00460 and LINC00525 were upregulated in LUAD, which improved the levels of FAM111B and ZWINT via hsa-mir-338 sponge, thus promoting the occurrence of cancer." (PMID 35406786, 2022).
LINC00525 also shares sentences with these, for which no sentence is quoted: tumor (2 papers); breast carcinoma (1); breast invasive carcinoma (1); leukaemia (1); lung squamous cell carcinoma (1); non-small cell lung carcinoma (1); oral squamous cell carcinoma (1); thyroid carcinoma (1).